TAF8 (TATA-box binding protein associated factor 8)
Description:
The TFIID basal transcription factor complex plays a major role in the initiation of RNA polymerase II (Pol II)-dependent transcription. TFIID recognizes and binds promoters with or without a TATA box via its subunit TBP, a TATA-box-binding protein, and promotes assembly of the pre-initiation complex (PIC). The TFIID complex consists of TBP and TBP-associated factors (TAFs), including TAF1, TAF2, TAF3, TAF4, TAF5, TAF6, TAF7, TAF8, TAF9, TAF10, TAF11, TAF12 and TAF13. The TFIID complex structure can be divided into 3 modules TFIID-A, TFIID-B, and TFIID-C. TAF8 is involved in forming the TFIID-B module, together with TAF5. Mediates both basal and activator-dependent transcription. Plays a role in the differentiation of preadipocyte fibroblasts to adipocytes, however, does not seem to play a role in differentiation of myoblasts. Required for the integration of TAF10 in the TAF complex. May be important for survival of cells of the inner cell mass which constitute the pluripotent cell population of the early embryo (By similarity).
Synonyms: TAFII-43; TAFII43; TBN; FLJ32821; TAF(II)43; II; NEDMLHB; TAF
Tractability: Small molecule: a structure with a bound ligand is known. PROTAC: its protein half-life has been measured.
Gene: Protein-coding gene on chromosome 6 (42,050,513 to 42,087,461, forward strand). Ensembl gene ENSG00000137413.
Subcellular location: Nucleus; Cytoplasm
Subcellular location (Human Protein Atlas): Nucleoplasm; Mid piece
Pathways (Reactome):
Gene expression (Transcription): RNA Polymerase II Pre-transcription Events; RNA Polymerase II Promoter Escape; RNA Polymerase II Transcription Initiation; RNA Polymerase II Transcription Initiation And Promoter Clearance; RNA Polymerase II Transcription Pre-Initiation And Promoter Opening; RNA polymerase II transcribes snRNA genes
Disease: HIV Transcription Initiation; RNA Polymerase II HIV Promoter Escape; Transcription of the HIV genome
Gene Ontology:
Molecular function: protein binding; RNA polymerase II general transcription initiation factor activity; protein heterodimerization activity
Biological process: DNA-templated transcription open complex formation; maintenance of protein location in nucleus; mRNA transcription by RNA polymerase II; positive regulation of transcription initiation by RNA polymerase II; regulation of fat cell differentiation; RNA polymerase II preinitiation complex assembly; transcription initiation at RNA polymerase II promoter
Cellular component: cytoplasm; nucleoplasm; nucleus; perinuclear region of cytoplasm; transcription factor TFIID complex
Genetic constraint (gnomAD): Loss-of-function variants: 38 observed, 29.94 expected, observed/expected ratio (o/e) 1.27, 90% interval 0.98 to 1.66. The upper end of that interval is the gene's LOEUF score, 1.66, which puts it in group 6 of 6, group 1 being the genes least tolerant of losing a copy. Missense variants: 351 observed, 344.27 expected, observed/expected ratio (o/e) 1.02, 90% interval 0.93 to 1.11. Synonymous variants: 145 observed, 138.25 expected, observed/expected ratio (o/e) 1.05, 90% interval 0.92 to 1.2.
Homologues: Orthologues: macaque TAF8 (99% identical), pig TAF8 (98% identical), dog TAF8 (98% identical), rabbit TAF8 (97% identical), guinea pig TAF8 (96% identical), rat Taf8 (95% identical), mouse Taf8 (95% identical), chimpanzee TAF8 (87% identical), tropical clawed frog taf8 (77% identical), zebrafish taf8 (73% identical), Drosophila melanogaster Taf8 (39% identical), Caenorhabditis elegans taf-8 (27% identical), and 1 more.
Diseases named in the same sentence as TAF8 in open-access papers:
TAF8 is named in the same sentence as 11 diseases in open-access papers, as found by Europe PMC text mining. Sharing a sentence is not in itself a finding about the gene and the disease. The quoted sentences say what the papers report.
Intellectual disability (2 papers, 2019 to 2021). "Recent exome sequencing studies have produced compelling evidence that pathogenic variants in TAF1, TAF2, TAF8 and TAF13 are linked to intellectual disability and microcephaly." (PMID 30948355, 2019). "First, variants in TAF1, TAF2, TAF8 and TAF13 have all been linked to intellectual disability and microcephaly." (PMID 30948355, 2019). "Intriguingly, the patient with intellectual disability expresses an unstable TAF8 protein in which the C-terminal last 49 WT amino acids of TAF8 are replaced by a 38 amino acid mutated sequence (which removes part of T2R2 and all of T2R3), caused by the frame shift, leading to TFIID dissociation." (PMID 34634302, 2021).
pancreatic ductal adenocarcinoma (2 papers, 2023). An infiltrating adenocarcinoma that arises from the epithelial cells of the pancreas. "In pancreatic ductal adenocarcinoma (PDAC), HNRNPC regulates the selective splicing of TATA box-binding protein-associated factor 8 (TAF8) in an m6A-dependent manner, thereby promoting tumor progression." (PMID 38102645, 2023). "Specifically, hnRNPC facilitates the alternative splicing of TAF8 by binding to TAF8 mRNA, resulting in the production of the pro‐metastatic TAF8 S isoform in pancreatic ductal adenocarcinoma." (PMID 37850412, 2023).
prostate carcinoma (1 paper, 2011). A carcinoma that arises from epithelial cells of the prostate gland. "In particular, RegNetB identified the regulators PAX4, BACH1, BACH2, MAZ and TAF8 as playing a central role in this prostate cancer gene expression data set." (PMID 21682879, 2011).
tumor (3 papers, 2011 to 2023). "These target genes are known to participate in tumor progression, but the suggested regulatory roles of PAX4, BACH1, BACH2, MAZ and TAF8 in the process is new." (PMID 21682879, 2011).
cancer (1 paper, 2023). A tumor composed of atypical neoplastic, often pleomorphic cells that invade other tissues. "Interestingly, mutation of the m6A sites within TAF8 disrupts the interaction between hnRNPC and the TAF8 transcript, leading to an increase in the anti‐metastatic TAF8 L isoform and a decrease in the TAF8 S isoform, thereby limiting the metastatic potential of cancer cells." (PMID 37850412, 2023).
neurodevelopmental disorder (1 paper, 2025). A behavioral and cognitive disorder with onset during the developmental period that involves impaired or aberrant development of intellectual, motor, or social functions. "TAF8 deficiency was recently reported as causing a severe neurodevelopmental disorder in eight patients." (PMID 39169228, 2025). "Finally, further investigation into TAF8’s function and mechanism of action could yield insights into their crucial biological and developmental roles in normal fetal development and possibly pave the way to potential therapeutic interventions for these devastating neurodevelopmental disorders." (PMID 39169228, 2025).
TAF8 also shares sentences with these, for which no sentence is quoted: co-infection (1 paper); infection (1); lung carcinoma (1); microcephaly (1); viral infection (1).